PRSS53 (serine protease 53)
Description:
In vitro can degrade the fibrinogen alpha chain of as well as pro-urokinase-type plasminogen activator.
Synonyms: POL3S; UNQ308
Tractability: Antibody: UniProt places it where antibodies can reach, with high confidence; UniProt predicts a signal peptide or a membrane-spanning region; its Gene Ontology location is reachable by antibodies, with medium confidence.
Gene: Protein-coding gene on chromosome 16 (31,083,437 to 31,089,628, reverse strand). Ensembl gene ENSG00000151006.
Subcellular location: Secreted
Gene Ontology:
Molecular function: protein binding; serine-type endopeptidase activity
Biological process: proteolysis
Cellular component: extracellular region
Genetic constraint (gnomAD): Loss-of-function variants: 56 observed, 58.42 expected, observed/expected ratio (o/e) 0.96, 90% interval 0.77 to 1.2. The upper end of that interval is the gene's LOEUF score, 1.2, which puts it in group 5 of 6, group 1 being the genes least tolerant of losing a copy. Missense variants: 688 observed, 715.67 expected, observed/expected ratio (o/e) 0.96, 90% interval 0.9 to 1.02. Synonymous variants: 273 observed, 289.07 expected, observed/expected ratio (o/e) 0.94, 90% interval 0.86 to 1.04.
Homologues: Orthologues: chimpanzee PRSS53 (95% identical), macaque PRSS53 (88% identical), dog PRSS53 (86% identical), pig PRSS53 (84% identical), guinea pig PRSS53 (84% identical), rabbit PRSS53 (81% identical), mouse Prss53 (80% identical), rat Prss53 (79% identical), tropical clawed frog prss53 (38% identical), Drosophila melanogaster CG8299 (13% identical), Drosophila melanogaster CG11192 (12% identical), Drosophila melanogaster Try29F (12% identical), and 26 more. Paralogues in human: PRSS36 (38% identical).
Diseases named in the same sentence as PRSS53 in open-access papers:
PRSS53 is named in the same sentence as 8 diseases in open-access papers, as found by Europe PMC text mining. Sharing a sentence is not in itself a finding about the gene and the disease. The quoted sentences say what the papers report.
diabetes (1 paper, 2013). "Of note, the Tmem229B, Prss53 and Ttc28 genes, which have not been linked to β-cell functions or diabetes, showed strong signals in untreated islets but were strongly suppressed by STZ." (PMID 23828045, 2013).
epidermolysis bullosa (1 paper, 2021). Epidermolysis bullosa (EB) is a group of genetic skin diseases that cause the skin to blister very easily. "Other transcripts are likely related to follicular (Pla2g2e, Prss53) and keratinocyte (Exph5) adhesion and migration, and Pla2g2e has been specifically related to skin disorders such as epidermolysis bullosa and skin fragility." (PMID 34823472, 2021).
psoriasis (1 paper, 2013). An autoimmune condition characterized by red, well-delineated plaques with silvery scales that are usually on the extensor surfaces and scalp. "Nevertheless, 7 of the PP-increased DEGs were associated with psoriasis susceptibility loci (LCE3D, IFIH1, GRHL3, IL12B, PRSS53, REL and NOS2), and 1 PP-decreased DEG was near a psoriasis susceptibility locus (SDC4)." (PMID 24260178, 2013).
cancer (2 papers, 2006 to 2021). A tumor composed of atypical neoplastic, often pleomorphic cells that invade other tissues. "In contrast, the roles of the serine proteases PRSS33 and PRSS53 have been less investigated in cancer progression, but there are indications that PRSS33 may play a role in tumor cell invasion." (PMID 34149812, 2021).
neurological disease (1 paper, 2025). "Also, 59 unique proteins were associated with AD, and 10 of them (17%) showed an association with AD and an additional neurological disease (CTF1, NSF and PRSS53 with PD; SIGLEC9 with ALS; CR1, CTSH, PARP1 and PVR with MS; LRRC37A2 with both PD and ALS; and IDUA with PD, ALS and MS)." (PMID 40037332, 2025).
PRSS53 also shares sentences with these, for which no sentence is quoted: tumor (2 papers); skin disorder (1); skin fragility (1).